CD44 (CD44 molecule (IN blood group))
Diseases named in the same sentence as CD44 in open-access papers (continued):
Sharing a sentence is not in itself a finding about the gene and the disease.
salivary gland mucoepidermoid carcinoma (3 papers, 2015 to 2017). A carcinoma that arises from the salivary glands. "Here, we demonstrated that the combination of ALDH activity and CD44 expression enables the identification of highly tumorigenic cells in salivary gland mucoepidermoid carcinoma." (PMID 26449187, 2015). "Adams and colleagues demonstrated that salivary gland mucoepidermoid carcinomas contain a small population of cancer stem cells with enhanced tumorigenic potential and are characterized by high ALDH activity and CD44 expression." (PMID 28008389, 2016). "Collectively, these data demonstrate that salivary gland mucoepidermoid carcinomas contain a small population of cancer stem cells with enhanced tumorigenic potential and that are characterized by high ALDH activity and CD44 expression." (PMID 26449187, 2015). "Collectively, these data indicate that the CD44/CD24 marker combination does not enable consistent identification of a unique population of highly tumorigenic cells in salivary gland mucoepidermoid carcinomas." (PMID 26449187, 2015). "Together, these results suggest that ALDH1, CD44, CD10, and CD24 are highly expressed in salivary gland mucoepidermoid carcinoma when compared to normal salivary gland and that expression of ALDH1, CD10, and CD24 may be differentially regulated in more aggressive cell types." (PMID 26449187, 2015).
skin atrophy (3 papers, 2010 to 2024). The degeneration and thinning of the epidermis and dermis. "As a result, defects in HA and CD44 play an important role in skin atrophy and the development of dermatoporosis." (PMID 39336075, 2024). "Suppression of CD44 leads to skin atrophy, but a combination of retinaldehyde (RAL) with HA fragments (HAFi) induces skin hyperplasia." (PMID 39336075, 2024). "Specific suppression of CD44 in keratinocytes leads to skin atrophy in transgenic mice, suggesting that CD44 plays an important role in the regulation of epidermal homeostasis." (PMID 37366799, 2023). "Our previous studies have shown that the topical application of HAFi reversed skin atrophy in dermatoporosis patients by a CD44-dependent mechanism." (PMID 37366799, 2023). "We have recently shown that intermediate size HA fragments (HAFi) reverse skin atrophy by a CD44-dependent mechanism." (PMID 21179550, 2010).
small cell neuroendocrine carcinoma (3 papers, 2011 to 2023). "We had found CD44 could regulate glucose metabolism in small cell neuroendocrine carcinoma which may have been induced by androgen deprivation therapy." (PMID 29029419, 2017).
spindle cell carcinomas (3 papers, 2008 to 2020). "Class A cell lines (referred to as CLA) are the pure spindle cell carcinomas exhibiting the EpCAM-CD24+CD44+CD133− surface phenotype." (PMID 26158412, 2015). "Histological examination of tissue sections reveals that unsorted SUM159 cells form highly invasive spindle-cell carcinomas, and this spindle-cell morphology is recapitulated in SUM159 tumors derived from 1 × 103 CD44+/CD24-/low/ESA+ cells." (PMID 18366788, 2008).
Splenomegaly (3 papers, 2021 to 2025). Abnormal increased size of the spleen. "The importance of DCs in regulating the CD8+ Treg compartment of naïve mice is supported by the notable reduction in the CD8+ CD44+ population in a mouse model lacking DCs that also develop an autoimmune phenotype, along with splenomegaly and antinuclear antibody production." (PMID 35784310, 2022).
Thrombocytopenia (3 papers, 2013 to 2015). A reduction in the number of circulating thrombocytes. "Antibody-induced thrombocytopenia can be caused by a number of different monoclonal anti-platelet antibodies, and we have recently observed that CD44 antibodies can also cause thrombocytopenia in mice." (PMID 23785450, 2013). "We have previously demonstrated that IM7 (an anti-CD44 commonly used in ameliorating murine models of inflammatory arthritis) can induce thrombocytopenia on its own." (PMID 23785450, 2013). "While each of these CD44 antibodies induced thrombocytopenia and reduced inflammation, the length and severity of the thrombocytopenia did not appear to mirror their therapeutic effect." (PMID 23785450, 2013). "In contrast, the IM7 CD44 antibody induced severe thrombocytopenia, which resolved approximately 4 days after the last injection, followed by a transient period of increased platelet counts." (PMID 23785450, 2013). "In addition to IVIg, we have also demonstrated that antibodies to some select cellular antigens including the CD44 antigen can ameliorate thrombocytopenia in the murine ITP model." (PMID 23940791, 2013). "CD44 antibody treatment was also able to reverse established inflammation, while thrombocytopenia induced by an anti-platelet antibody targeting the GPIIbIIIa platelet antigen, could not mediate this effect." (PMID 23785450, 2013). "While we are unable to rule out the possibility that antibody-induced thrombocytopenia contributes to some of the therapeutic effect, it seems reasonable to suggest that thrombocytopenia-independent mechanisms likely contribute to the primary ameliorative actions of CD44 antibodies." (PMID 23785450, 2013). "It has been suggested that since CD44 is not expressed in human platelets, anti-CD44 antibodies should not induce thrombocytopenia in patients." (PMID 25954275, 2015). "Unlike mice, human platelets do not appear to express CD44 thus development of a CD44 antibody to treat RA would not be expected to induce thrombocytopenia in humans." (PMID 23785450, 2013). "Humans are not known to express CD44 on platelets, and are therefore unlikely to develop thrombocytopenia after CD44 antibody treatment." (PMID 23785450, 2013).
tongue cancer (3 papers, 2013 to 2025). A malignant neoplasm affecting the tongue. "From these candidates, we further validated CD44 at translational level in an independent cohort of 100 patients with tongue cancer followed-up beyond 10 years." (PMID 33976322, 2021).
vascular tumors (3 papers, 2019 to 2020). "CD44 is a cancer stem cell marker whose expression is correlated with pathogenesis in vascular tumors." (PMID 32293476, 2020). "IGF2BP3 might also be correlated with the pathogenesis of vascular tumors via CD44 mRNA stabilization and translation." (PMID 32293476, 2020).
vitiligo (3 papers, 2022 to 2025). Generalized well circumscribed patches of leukoderma that are generally distributed over symmetric body locations and is due to autoimmune destruction of melanocytes. "CD44 expression is important for the survival and activation of memory T cells; CXCL10 may also play a critical role in driving CD8+ memory T cells into the vitiligo epidermis." (PMID 35096274, 2022).
acute coronary syndrome (2 papers, 2021 to 2025). Signs and symptoms related to acute ischemia of the myocardium secondary to coronary artery disease. "A recent clinical study revealed that the expression of HYAL2 and CD44 in peripheral blood mononuclear cells (PBMCs) increased in acute coronary syndrome (ACS), especially in patients with plaque erosion compared with stable CAD and healthy people." (PMID 33644134, 2021).
acute promyelocytic leukemia (2 papers, 2016 to 2024). An aggressive form of acute myeloid leukemia (AML), characterized by arrest of leukocyte differentiation at the promyelocyte stage, due to a specific chromosomal translocation t(15;17) in myeloid cells. "Notably, Fg deposition in acute promyelocytic leukemia is mediated by Fg binding to CD44 on APL blasts and NB4 cells." (PMID 38779081, 2024).
acute respiratory distress syndrome (2 papers, 2019 to 2021). Progressive and life-threatening pulmonary distress in the absence of an underlying pulmonary condition, usually following major trauma or surgery. "In acute respiratory distress syndrome (ARDS) models, the administration of MSC-derived CD44+ EVs reduced the lung injury." (PMID 33796536, 2021). "In an acute respiratory distress syndrome (ARDS) model, alveolar macrophages treated with MSC-derived CD44+ EVs also reduced lung injury." (PMID 31214185, 2019).
adrenocortical adenoma (2 papers, 2015 to 2022). "However, immunohistochemistry confirmed that the stemness markers SOX2, CD44, and OCT4 were highly expressed in MCMT with greater adrenocortical adenoma density than in PCC." (PMID 36187098, 2022).
adrenocortical tumor (2 papers, 2015 to 2017). "The aim of this work is to characterize the expression of the metabolism-related proteins MCT1, MCT2, MCT4, CD147, CD44, GLUT1 and CAIX in a series of pediatric adrenocortical tumors." (PMID 28969033, 2017).
alcohol (2 papers, 2006 to 2024). "Consistent with this, we observed decreased expression of natural killer cell-related genes, including CD44, IL15R, CD2 and CCL5, in alcohol-associated cirrhotic liver samples." (PMID 17121680, 2006).
Anxiety (2 papers, 2020 to 2025). Intense feelings of nervousness, tension, or panic often arise in response to interpersonal stresses. "Furthermore, antagonism of CD44 reduced long-term potentiation in hippocampal neurons, and CD44-HA interactions contribute to pain sensitivity, as well as anxiety-like behavior." (PMID 32825309, 2020).
Ascites (2 papers, 2014 to 2015). Accumulation of fluid in the peritoneal cavity (between the layers of the peritoneum that lines the abdomen). "EpCAM and CD44 are oncogenic glycoproteins commonly expressed by EOC solid tumours and ascites tumour cells." (PMID 26260289, 2015). "The expression of CD117, Oct4 and JAGGED was significantly up in paclitaxel-treated ascites tumor cells, while there was a trend in the increased expression of EpCAM, CD44 and NANOG but it was not significant compared to untreated control." (PMID 24886434, 2014).
bacteremia (2 papers, 2023 to 2024). "Monocytes from patients with S. aureus bacteremia revealed preserved pro-inflammatory responsiveness to S. aureus stimulation ex vivo, expressed increased CD44 mRNA but no other glycoprotein of the tolerance signature was differentially expressed." (PMID 37063823, 2023). "Among the top differentially expressed genes in young infants with UTI without bacteremia, only two genes directly annotated to immune response were upregulated, i.e., leukotriene A4 hydrolase (LTA4H) and CD44 molecule." (PMID 38732074, 2024).
bone sarcoma (2 papers, 2013 to 2023). A sarcoma that arises from the bone. "Our findings show the existence in human primary bone sarcomas of highly proliferative endothelial cells expressing CD31, CD44, CD105, CD146 and CD90 markers." (PMID 24216983, 2013).
cerebral infarct (2 papers, 2024 to 2025). "Interestingly, the spatial association of OPN positive myeloid cells to bordering CD44 positive cells was also observed in human cerebral infarctions in the stage of advanced macrophage resorption." (PMID 39043661, 2024). "A recent animal experiment showed that PCSK9 inhibitor evolocumab improved neurobehavioral functions and reduced cerebral infarct volumes, which may be mediated by attenuating neuroinflammation through activation of the GPNMB/CD44 pathway." (PMID 41368357, 2025).
cervical squamous cell carcinoma (2 papers, 2023 to 2024). A squamous cell carcinoma arising from the cervical epithelium. "The bioinformatics analysis showed a high expression of CD44 on cervical squamous cell carcinoma and endocervical adenocarcinoma (CESC) tissues as compared to normal cervical tissue after comparing tumor tissue data from TCGA and normal tissue data from GTEx." (PMID 37283735, 2023). "Moreover, Chi-square test identified tumor stage, HPV type, and tumor size were positively correlated with SPP1 expression, while tumor size and numbers of positive nodes were related to CD44 expression in CC patients from The Cancer Genome Atlas cervical squamous cell carcinoma (TCGA-CESC)." (PMID 38346944, 2024).
chordoma (2 papers, 2017 to 2023). Chordomas are rare malignant tumors arising from embryonic remnants of the notochord in axial skeleton. "Our analysis revealed that the interaction between FN1 and CD44, as well as the interaction between FN1 and ITGA4/ITGB1, plays prominent roles in the communication network of both primary and recurrent chordomas." (PMID 37784253, 2023).
chronic gastritis (2 papers, 2011 to 2017). Inflammation of the stomach that is chronic in nature. "Moreover, Hp, either directly or through the induction of a local inflammatory response, may be responsible for the increased expression of CD44 and Musashi-1, suggesting a possible link between CD44/Musashi-1 expression and chronic gastritis." (PMID 21829201, 2011). "In contrast, the distribution of three genotypes and CD44 protein expression in chronic gastritis and precancerous gastric lesions were not statistically significant." (PMID 29445738, 2017).
chronic lymphoid leukemia (2 papers, 2013 to 2022). "For instance, in chronic lymphoid leukemia, patient-derived exosomes have elevated CD19, CD31, CD44, CD82, HLA-A to D, levels, while low levels of CD21, CD49c, and CD63." (PMID 35399522, 2022). "In chronic lymphoid leukemia, upregulated levels of CD19 and CD37 have been observed; in AML patients, EVs rich in myeloblastic markers like CD34, CD33, and CD117 have been seen; while multiple myeloma patients have been screened based on EVs with CD38, CD138, CD44 and CD147 markers." (PMID 35399522, 2022).
chronic pancreatitis (2 papers, 2017). A chronic inflammatory process causing damage and fibrosis of the pancreatic parenchyma. "So far, there is very little data regarding the comparison of the expression of CD24, CD44, and CD133 in PDAC and chronic pancreatitis (CP)." (PMID 28659655, 2017). "Surgical specimens from 23 patients with PDAC and 15 patients with chronic pancreatitis after pancreatic resection were stained with CD24, CD44, and CD133 antibodies." (PMID 28659655, 2017).
co-infection (2 papers, 2021 to 2025). "Co-infection was also exemplified by a consistently increased effector-memory phenotype (i.e., CD44+ KLRG1+) of the GP33-specific CD8+ T cells in blood." (PMID 33458613, 2021). "Consistently, the results showed that NGOs displayed a significant upregulation of TFF1, VIL1, and Lgr5 at 24 h after co-infection of H. pylori with EBV and a downregulation of CD44 and Axin 2 compared to the H. pylori or EBV-alone groups." (PMID 40833108, 2025). "Cytosplore analysis based on the markers CD44, CD62L, and KLRG1 revealed that at the peak of the effector response, the phenotype of the GP33-specific CD8+ T cells in the blood upon LCMV Armstrong infection resembled the phenotype of the GP33-specific CD8+ T cells that develop during co-infection." (PMID 33458613, 2021).
cognitive decline (2 papers, 2021 to 2025). "In contrast, Rapid Decline showed increased β-amyloid (bA), glial and inflammatory markers (CD44, PLXNB1), and stress- and mitochondrial-related proteins (GSTP1, AK4, HSPB2, FBXO2, IGFBP5), which have been associated with neurodegeneration and cognitive decline in AD." (PMID 40799531, 2025).
Duchenne muscular dystrophy (2 papers, 2017 to 2022). Duchenne muscular dystrophy (DMD) is a neuromuscular disease characterized by rapidly progressive muscle weakness and wasting due to degeneration of skeletal, smooth and cardiac muscle. "CD29+, CD44+, CD59+, and CD90+ cells from menstrual blood are capable of differentiating into myoblasts/myocytes and conferring human dystrophin expression in the murine model for Duchenne muscular dystrophy." (PMID 28706537, 2017). "CD4+ and CD8+ T cells have also been associated with muscle degeneration and fibrosis in the mdx mice, a natural mutant that does not express dystrophin and Duchenne muscular dystrophy (DMD) homolog, by induction of specific antigen activation of CD44+ cells homing into the damaged tissue." (PMID 35740942, 2022).
endometrial adenocarcinoma (2 papers, 2012 to 2021). "CD133-positive cells purified from endometrial adenocarcinomas displayed a higher level of proteins associated with tumor progression (e.g., matrix metalloproteases, interleukin-8, CD44, and CXCR4)." (PMID 34063525, 2021). "Among the previous analyses of CD44 in endometrial adenocarcinoma, some investigators found no relation between CD44v6 and clinicopathological parameters and thought that CD44v6 was not an adverse predictive factor." (PMID 22784357, 2012).
endotoxemia (2 papers, 2013 to 2015). "For example, neutrophils from Rab27a-deficient mice display reduced surface expression of CD44, and as such were found to have impaired adhesion within liver sinusoids in response to endotoxemia." (PMID 25741341, 2015). "Analysis of surface expression levels revealed equivalent quantities of CD44 expression regardless of the stimulus, whereas Mac-1 expression was significantly reduced during endotoxemia as a consequence of high circulating IL-10." (PMID 25741341, 2015). "Menezes and colleagues performed a more in-depth functional analysis of CD44–HA interaction using confocal intravital microscopy in mouse models of endotoxemia and Gram-negative bacterial sepsis." (PMID 25741341, 2015).
follicular adenoma (2 papers, 2015 to 2025). "Among these is the CD44 isoform CD44v6, whose expression correlates with metastatic potential and which has been shown to be negative in follicular adenoma but positive in several thyroid malignancies; membranous and cytoplasmic CD44v6 positivity has been documented in PTC." (PMID 26550511, 2015).
gastric cardia carcinoma (2 papers, 2014 to 2025). A carcinoma that arises from epithelial cells of the cardia of stomach. "Additionally, we found that CD44-positive CTCs were more often detected in patients with gastric cardia cancer." (PMID 24963492, 2014). "For instance, CD24+CD44+EpCAM+ gastric CSCs are significantly associated with poor patient prognosis, and the NNMT+/AQP5+ phenotype could serve as a potential diagnostic marker for gastric cardia cancer." (PMID 40665579, 2025). "Finally, patients with gastric cardia cancer were more likely to have CD44-positive CTCs than gastric noncardia cancer patients (16 out of 19 patients and 3 out of 8 patients, resp.; P = 0.027)." (PMID 24963492, 2014).
glomerulonephritis (2 papers, 2014 to 2019). A renal disorder characterized by damage in the glomeruli. "ICAM-1 expression is reported to be upregulated by CD44 and associated with leukocyte infiltration in human glomerulonephritis." (PMID 24595031, 2014). "Given the coexpression of CD9 with the activated-PEC marker CD44 during proliferative glomerulonephritis, we next investigated whether CD9 was involved in other diseases with PEC phenotypic changes, like FSGS35,36." (PMID 31341160, 2019).
Glucose intolerance (2 papers, 2013 to 2022). Glucose intolerance (GI) can be defined as dysglycemia that comprises both prediabetes and diabetes. "Our results indicate that the underlying susceptibility to glucose intolerance and hepatosteatosis is not caused by CD44 and that the effects of CD44 are only evident in cases of genetic susceptibility." (PMID 35410390, 2022).
HCMV infection (2 papers, 2014 to 2017). "HCMV infection significantly increased stem cell frequency in the CD44+387 cells as well as in the CD133+ fraction of 3832 cells." (PMID 25549333, 2014). "Nevertheless, HCMV infection with AD169 did reduce the steady state levels of caveolin-1 as well as CD98, CD44, and CD81 as shown by Western blotting of whole cell lysates." (PMID 29121670, 2017).
hepatitis C (2 papers, 2022 to 2024). "While as in hepatitis C, the CD44 expression is amplified in infected cells with HCV when induced with HA that increases IP-10 (gamma interferon-inducible protein 10) expression via CD44–TLR2–MyD88 interactions." (PMID 34980167, 2022). "In viral diseases such as HIV and hepatitis C, CD44 plays the opposite role in infection." (PMID 34980167, 2022).